Y_RNA (Y RNA )
Gene: Miscellaneous RNA gene on chromosome 9 (75,181,520 to 75,181,621, reverse strand). Ensembl gene ENSG00000200041.
Homologues: Orthologues: chimpanzee Y_RNA (99% identical), macaque Y_RNA (93% identical). Paralogues in human: Y_RNA (90% identical), RNY3P14 (88% identical), Y_RNA (88% identical), RNY3 (87% identical), RNY3P1 (87% identical), Y_RNA (87% identical), Y_RNA (86% identical), Y_RNA (85% identical), RNY3P5 (84% identical), Y_RNA (84% identical), Y_RNA (83% identical), RNY3P11 (82% identical), and 94 more.